ITCH (itchy E3 ubiquitin protein ligase)
Diseases named in the same sentence as ITCH in open-access papers (continued):
Sharing a sentence is not in itself a finding about the gene and the disease.
heart failure (2 papers, 2021 to 2022). Inability of the heart to pump blood at an adequate rate to meet tissue metabolic requirements. "In our study, increased MDM2 protein expression after MI and decreased ITCH expression after CHF could promote NF-kB activity, which in turn is known to induce heart failure by triggering chronic inflammation." (PMID 34947961, 2021).
Hepatic steatosis (2 papers, 2015 to 2025). Steatosis is a term used to denote lipid accumulation within hepatocytes. "In summary we suggest that the modulation of ITCH at hepatic level is an interesting target to be further exploited for effects on hypercholesterolemia and hepatic steatosis." (PMID 25777360, 2015). "Beyond lipids, ITCH is essential for maintaining BCAA catabolism, ITCH‐deficient mice develop hepatic steatosis and insulin resistance, while clinical data link ITCH dysfunction in obese individuals to impaired BCAA degradation, elevated circulating BCAAs, and severe hepatic steatosis." (PMID 41362701, 2025).
nasopharyngeal carcinoma (2 papers, 2022 to 2025). A carcinoma arising from the nasopharyngeal epithelium. "A recent vitro experimental investigation found that circ-ITCH might further up-regulate PTEN in nasopharyngeal cancer (NPC) via sponging miR-214, indicating that it can prevent NPC progression by blocking the PI3K/Akt pathway." (PMID 35910224, 2022). "Recent research has indicated that ITCH mediates SIX1 ubiquitination and influences the development of nasopharyngeal carcinoma via the CDC27-cyclin B1 signaling pathway." (PMID 40170095, 2025).
osteoarthritis (2 papers, 2021 to 2023). A noninflammatory degenerative joint disease occurring chiefly in older persons, characterized by degeneration of the articular cartilage, hypertrophy of bone at the margins and changes in the synovial membrane. "One group reported that mice with ITCH deficiency in macrophages exhibited more severe joint damage compared with wildtype mice after post-traumatic osteoarthritis surgery." (PMID 37359559, 2023). "ITCH protein levels were decreased during post-traumatic osteoarthritis." (PMID 37359559, 2023). "We will also keep working to prove whether circ-ITCH regulates other bone degeneration diseases, such as osteoarthritis and bone senescence." (PMID 33795657, 2021). "ITCH expression was decreased in osteoarthritis samples compared with normal cartilaginous samples, whereas JAG1 expression was elevated in osteoarthritis specimens." (PMID 37359559, 2023).
osteosarcoma (2 papers, 2020 to 2022). A usually aggressive malignant bone-forming mesenchymal neoplasm, predominantly affecting adolescents and young adults. "In recent years, circ-ITCH has been identified to regulate the progression of osteosarcoma." (PMID 35327551, 2022). "We aimed to investigate the possible role ofcir-ITCH in osteosarcoma." (PMID 31960764, 2020). "In addition, the results showed that cir-ITCH could promote themigration, invasion, and growth of osteosarcoma cells." (PMID 31960764, 2020).
Sepsis (2 papers, 2022 to 2025). Sepsis is defined as life-threatening organ dysfunction caused by a dysregulated host response to infection. "This study revealed a reduced expression level of ITCH in the diagnostic model of sepsis combined with ALF." (PMID 40781631, 2025). "The GSEA results indicated ITCH was predominantly implicated in primary immunodeficiency, FcγR-mediated phagocytosis, and the T cell receptor signaling pathway inside sepsis dataset." (PMID 40781631, 2025). "This study reveals the potential value of GABARAP and ITCH as diagnostic biomarkers associated with pyroptosis in sepsis and ALF." (PMID 40781631, 2025). "We found GABARAP and ITCH may serve as diagnostic biomarkers for pyroptosis in sepsis combined with ALF, suggesting their potential involvement in the initiation and advancement of sepsis combined with ALF through cellular immunomodulatory pathways." (PMID 40781631, 2025). "Machine learning revealed that GABARAP and ITCH may serve as diagnostic biomarkers for pyroptosis in sepsis combined with ALF." (PMID 40781631, 2025). "In conclusion, GABARAP and ITCH may serve as promising pyroptosis-related diagnostic biomarkers for sepsis and ALF." (PMID 40781631, 2025). "Machine learning indicated that GABARAP and ITCH may be hub genes implicated in the pathological mechanisms of sepsis and ALF." (PMID 40781631, 2025). "Our results suggest that ITCH may serve as a novel therapeutic target for preventing septic cardiomyopathy in patients with sepsis." (PMID 39802494, 2022). "GABARAP and ITCH may have extensive regulatory effects on numerous biological pathways, particularly concerning cellular immune function, which could impact the pathogenesis of sepsis combined with ALF." (PMID 40781631, 2025). "Additionally, further animal experiments have indicated that GABARAP and ITCH may mediate the pathogenesis of sepsis combined with ALF." (PMID 40781631, 2025). "Animal experiments further validated that in the process of sepsis combined with ALF, the expression level of GABARAP is elevated, while the expression level of ITCH is diminished." (PMID 40781631, 2025). "Considering the intricate relationship between immune cells and sepsis as well as ALF, the correlation of GABARAP and ITCH with various immune cells was analyzed." (PMID 40781631, 2025). "The examination of immune cell infiltration indicated that immune dysregulation is present in both sepsis and ALF and preliminarily suggested that GABARAP and ITCH may be pivotal in cellular immunity responses, particularly those mediated by T cells." (PMID 40781631, 2025). "But no research has yet substantiated the involvement of ITCH in the pathophysiology of sepsis combined with ALF, requiring further investigation." (PMID 40781631, 2025).
thyroid nodule (2 papers, 2021 to 2023). A small circumscribed mass in the THYROID GLAND that can be of neoplastic growth or non-neoplastic abnormality. "When comparing thyroid nodule patients with the GG genotype to those with the GA and AA alleles, the expression of circ-ITCH and CBL was significantly upregulated, whereas the expression of miR-22-3p was significantly downregulated." (PMID 37370928, 2023). "The expression of circ-ITCH and CBL was remarkably elevated, while the expression of miR-22-3p was notably suppressed in the tissue samples of thyroid nodule patients carrying the GG genotype when compared with patients carrying the GA and AA alleles." (PMID 34531437, 2021).
3MC syndrome (1 paper, 2023). "Developmental delay is indicated in 3MC syndrome, LAD type 2, Cohen syndrome, Kabuki syndrome, Barth syndrome, P14 deficiency, adenosine deaminase acting on RNA 1 (ADAR1) deficiency, HIES with PGM3 mutations, PNP deficiency, MKD, DGS, NBS, and ITCH deficiency." (PMID 37102642, 2023).
anaplastic thyroid carcinoma (1 paper, 2023). "In addition, ITCH has been detected to be over-expressed in various human cancers such as ovarian, breast, sarcomas, and anaplastic thyroid carcinoma, and ITCH depletion could potentiate the effect of chemotherapeutic drugs." (PMID 36918822, 2023).
ataxia telangiectasia (1 paper, 2014). Ataxia-telangiectasia is the association of severe combined immunodeficiency (affecting mainly the humoral immune response) with progressive cerebellar ataxia. "The identification of the role of ATM on ITCH signaling may be relevant as it is tempting to speculate that the alteration of ITCH activity regulation due to the absence of ATM kinase activity may contribute to the Ataxia Telangiectasia pathogenesis." (PMID 25594035, 2014).
Bardet-Biedl syndrome (1 paper, 2021). A ciliopathy with multisystem involvement. "Additionally, they have also identified gene mutations in ITCH and CEP164 in two patients, demonstrating ITCH-related syndrome and Bardet–Biedl syndrome." (PMID 34589502, 2021).
cervical squamous cell carcinoma (1 paper, 2024). A squamous cell carcinoma arising from the cervical epithelium. "Interestingly, upregulation of ITCH has been associated with cervical squamous cell carcinoma progression." (PMID 38597989, 2024).
colon cancer (1 paper, 2020). "Further, low expression of circ‐ITCH in colon cancer represses the activation of MAPKs and alleviates the gene expression of ITCH thereby affecting the multiplication process." (PMID 32515024, 2020).
colorectal tumor (1 paper, 2016). "Yet, cir-ITCH was found to be able to increase the level of ITCH that can inhibit the Wnt/β-catenin pathway and block colorectal tumor progression." (PMID 27642518, 2016).
COVID-19 (1 paper, 2024). A disease caused by infection with severe acute respiratory syndrome coronavirus 2. "Given that the lungs are the primary target of SARS-CoV-2 and lung failure is a leading cause of mortality in COVID-19 patients, we analyzed ITCH expression across various lung cell types." (PMID 39677672, 2024). "Using single-nucleus RNA sequencing data from a published database, which includes over 116,000 nuclei from the lungs of nineteen individuals who died from COVID-19 and seven control individuals, we found that ITCH is ubiquitously expressed in lung cells." (PMID 39677672, 2024).
Crohn disease (1 paper, 2023). A gastrointestinal disorder characterized by chronic inflammation involving all layers of the intestinal wall, noncaseating granulomas affecting the intestinal wall and regional lymph nodes, and transmural fibrosis. "ITCH might regulate NOD2 signaling, which could explain the bowel inflammation observed in these patients with ITCH deficiency since NOD is associated with activation of the innate immune system and its mutations have been identified in patients with Crohn’s disease." (PMID 36911671, 2023).
endometriosis (1 paper, 2025). The growth of functional endometrial tissue in anatomic sites outside the uterine body. "ITCH, a ubiquitin E3 ligase involved in endometriosis, is downregulated in this condition and, when overexpressed, enhances the ubiquitination of ITGB3, affecting the proliferation and invasion capabilities of ectopic cells." (PMID 40508002, 2025). "The opposing expressions of ITCH and ITGB3 suggest that dysregulation of the ubiquitin process may play a crucial role in endometriosis pathogenesis." (PMID 40508002, 2025).
HCMV infection (1 paper, 2019). "In addition to ITCH, UL42 interacted with Neural Precursor Cell Expressed, Developmentally Down-Regulated 4 (NEDD4)- family E3 ligases NEDD4 and NEDD4-like (NEDD4L), which were degraded during early HCMV infection." (PMID 31873071, 2019).
hepatitis C virus infection (1 paper, 2022). A viral infection caused by the hepatitis C virus. "In Hepatitis C virus infection, for instance, circ-ITCH expression was positively correlated with liver enzymes AST, ALT (p < 0.001) and child grade." (PMID 35910224, 2022).
Hirschsprung disease (1 paper, 2022). Hirschsprung disease (HSCR) is a congenital intestinal motility disorder that is characterized by signs of intestinal obstruction due to the presence of an aganglionic segment of variable extent in the terminal part of the colon. "Circ-ITCH has been reported to play well-defined regulatory roles in bone illnesses, cardiac diseases, diabetic microangiopathy, and Hirschsprung disease, indicating that they could be therapeutically targeted." (PMID 35910224, 2022).
Hypercholesterolemia (1 paper, 2015). An increased concentration of cholesterol in the blood. "Thus, modulation of ITCH may provide a target for the treatment of hypercholesterolemia and hyperlipidemia." (PMID 25777360, 2015).
immune deficiency (1 paper, 2019). "In summary, AK2 joins RAG1, ADA as well as ITCH and RMRP genes in the list of known causes of immune deficiency in the Amish population." (PMID 31673062, 2019).
influenza (1 paper, 2024). An acute viral infection of the respiratory tract, occurring in isolated cases, in epidemics, or in pandemics; it is caused by serologically different strains of viruses (influenzaviruses) designated A, B, and C, has a 3-day incubation period, and usually lasts for 3 to 10 days. "ITCH is a ubiquitin ligase enzyme involved in immune responses, DNA repair, and cellular differentiation and was found critical for influenza viral entry and uncoating processes." (PMID 38257829, 2024).
intraductal carcinoma (1 paper, 2014). "Our data show that while low ITCH levels were detected in normal, hyperplastic and intraductal carcinoma tissue samples, high ITCH expression levels were seen in infiltrating or invasive ductal carcinoma samples as well as in samples that metastasized to secondary organs." (PMID 25350971, 2014).
invasive breast carcinoma (1 paper, 2014). A carcinoma that infiltrates the breast parenchyma. "To confirm that the observed phenotypes of ITCH depletion are not cell specific, we knocked down ITCH in the MDA-MB231 invasive breast cancer cells." (PMID 25350971, 2014).
ischemic cardiomyopathy (1 paper, 2021). Ischemic cardiomyopathy is a cardiomyopathy in which a weakness in the muscle of the heart due to inadequate oxygen delivery to the myocardium with coronary artery disease being the most common cause. "In accordance with the results obtained from the study performed on human cardiac tissue of patients with ischemic cardiomyopathy, the mRNA and protein expression of ITCH was reduced following CHF in the murine model." (PMID 34947961, 2021).
liver cancer (1 paper, 2022). An epithelial or non-epithelial malignant neoplasm that arises from the liver. "Studies have confirmed that under high cell density, the progression of liver cancer can be inhibited by the miR-21 − YOD1 − ITCH − LATS signal axis." (PMID 35642058, 2022).
lymphoma (1 paper, 2016). A malignant (clonal) proliferation of B- lymphocytes or T- lymphocytes which involves the lymph nodes, bone marrow and/or extranodal sites. "It is therefore tempting to speculate that changes in USP9x activity might have a more significant effect on ITCH activity in lymphoma." (PMID 27462448, 2016).
Myocardial fibrosis (1 paper, 2020). "Calhex 231, a CaSR inhibitor, suppresses the ITCH-ubiquitin proteasome and TGFβ1/SMADs pathway, thus inhibiting the proliferation of cardiac fibroblasts, reducing collagen deposition, and decreasing glucose-induced myocardial fibrosis." (PMID 33110392, 2020).
osteoporosis (1 paper, 2021). A condition of reduced bone mass, with decreased cortical thickness and a decrease in the number and size of the trabeculae of cancellous bone (but normal chemical composition), resulting in increased fracture incidence. "The aim of this study was to clarify the functional roles and mechanisms of the circ-ITCH regulating osteogenic differentiation of osteoporosis." (PMID 33795657, 2021). "In this study, we firstly found that circ-ITCH was down‐regulated in osteoporosis but up‐regulated in osteogenic differentiation of hBMSCs." (PMID 33795657, 2021). "Taken together, these results demonstrated circ-ITCH overexpression could prevent osteoporosis progression in vivo." (PMID 33795657, 2021). "Our results highlighted the potential of circ-ITCH in osteogenic differentiation and could potentially protect patients from osteoporosis." (PMID 33795657, 2021). "In this study, we aimed at investigating the expression and function of circ-ITCH in osteoporosis." (PMID 33795657, 2021). "Thus, in this study, we hypothesize that circ-ITCH may be involved in osteoporosis and may regulate the hBMSCs osteogenic differentiation by interacting with miR-214." (PMID 33795657, 2021). "Furthermore, circ-ITCH overexpression stimulated hBMSCs osteogenic differentiation in vitro and partially attenuated the bone loss of femurs and increased BMD values of OVX mice, suggesting that upregulation of circ-ITCH could prevent osteoporosis." (PMID 33795657, 2021).
pancreatic ductal adenocarcinoma (1 paper, 2016). An infiltrating adenocarcinoma that arises from the epithelial cells of the pancreas. "ITCH down-regulation (and consequently reduction of HER3 ubiquitination and degradation) could maintain high HER3 expression in pancreatic ductal adenocarcinoma, driving metastasis formation via HER3 signaling." (PMID 27203743, 2016).
preeclampsia (1 paper, 2014). Preeclampsia is a hypertensive disorder of pregnancy that is characterized by new-onset hypertension with proteinuria presenting after 20 weeks of gestation, and depending on mild or severe forms may initially present with severe headache, visual disturbances, and hyperreflexia. "Furthermore, we could find only 5 genes (DAPK3, DUSP1, PAPPA2, ITCH, DENND2D) that overlapped with our gender-specific analysis of our data of all early and late combined preeclampsia samples." (PMID 25247495, 2014).
vertebral disc disease (1 paper, 2020). "Analysis using protein‐protein interaction (PPI) network and KEGG suggested that ITCH was not only at the core of gene interaction network, but also significantly enriched in the TNF signalling pathway, which has been proposed to be involved in the inter‐vertebral disc disease (IVDD) regulation." (PMID 32845084, 2020).